YAP1 (Yes1 associated transcriptional regulator)
Diseases named in the same sentence as YAP1 in open-access papers (continued):
Sharing a sentence is not in itself a finding about the gene and the disease.
melanoma (continued). "We analyzed paired melanoma and adjacent tissue samples from 23 patients 18 acral melanomas, 2 sun-exposed melanomas and 3 unclear-subset melanomas using RNA-seq and found that the Hippo-YAP1 signaling pathway was a top upregulated pathway in melanoma compared with paired adjacent tissues." (PMID 38169595, 2024). "However, an increased number of p-AKT+ cells was found in the melanomas containing YAP1-overexpressing CAFs." (PMID 38308096, 2024). "We also found that a MEK inhibitor mediated the translocation of YAP1 in melanoma cells, suggesting that YAP1 inhibition may sensitize melanoma to trametinib." (PMID 38169595, 2024). "To obtain a global picture of the underlying mechanisms by which YAP1 regulates the functional properties of CAFs and identify YAP1-regulated genes that are involved in a CAF-elicited melanoma program, we performed RNA-Seq to compare the gene expression profiles between GFP/M50 and shYAP1-GFP/M50." (PMID 38308096, 2024). "Similarly, YAP1 was recently shown to correlate with melanoma proliferation and resistance to MAPK inhibitors, and it is considered a potential target to overcome therapy resistance." (PMID 37174717, 2023). "Indeed, we observed that miR-195-5p expression level is negatively correlated with both genes in melanoma patients, reinforcing the finding that miR-195-5p/CCND1 and miR-195-5p/YAP1 axis are involved in human melanoma progression." (PMID 37174717, 2023). "Interestingly, YAP1-driven RTK overexpression reflects a melanoma stem-cell-like phenotype and YAP1-mediated MAPKi resistance relies on molecular programs that characterize stem cell-like cellular states." (PMID 35798875, 2022). "Interestingly, some CCLE melanoma cell lines showed intermediate YAP1/TAZ scores, but high MAPKi sensitivity." (PMID 35798875, 2022). "While YAP1 is not commonly mutated in human melanoma, YAP1 amplifications and mutations have been observed, and YAP staining in primary melanoma has been shown to significantly correlate with reduced patient survival." (PMID 35768444, 2022). "We further used a genome-wide CRISPR/Cas9 screen to identify vulnerabilities of YAP1/TAZ-driven melanoma cell lines and validated a sulfate transporter as an attractive therapeutic target whose inhibition overcomes YAP1/TAZ-driven mechanisms of MAPKi resistance." (PMID 35798875, 2022). "In the A375 melanoma cell line, dabrafenib strongly inhibited YAP1 expression (Mean Diff." (PMID 35956175, 2022). "Moreover, YAP5SA melanoma cells showed a sharp depletion of the proliferative and enrichment of the invasive gene signature, highlighting YAP1/TAZ as a potential driver of these phenotype switches." (PMID 35798875, 2022). "In addition, the effects of LTBP4 overexpression on inhibiting CTGF, Cyr61 and Birc5 expression, promoting the apoptosis, and inhibiting the metastasis and proliferation of melanoma cells were reversed by the overexpression of YAP1 or MST1." (PMID 35252214, 2021). "Interestingly, YAP1 which has already been identified as melanoma growth‐promoting gene was also found (Table EV3)." (PMID 33724679, 2021). "Previous study also points out that the increase of YAP1 in tumors with BRAFV600E mutation is a biomarker indicative of poor early response of patients, suggesting the potential of the expression of YAP1 in PLX 4032 drug-resistant melanoma as a novel research direction." (PMID 33996543, 2021). "Similarly, high levels of RhoA signaling, coupled with elevated activation of MRTFA and YAP1, promotes BRAFi resistance in dedifferentiated melanoma cell lines characterized by a decreased expression of melanocyte lineage genes." (PMID 32466585, 2020). "The YAP1 inhibitor Verteporfin is efficient in preclinical models of kidney fibrosis and it has been exploited as a molecular target in a pre-clinical model of melanoma, where it prevents the fibrotic phenotype induced by oncogenic BRAF inhibition." (PMID 32466585, 2020).
melanoma (continued). "Moreover, combined treatment with BRAFi and the YAP1 inhibitor Verteporfin reduces tumor growth in vivo, confirming YAP1 as an important resistance factor in melanoma." (PMID 32466585, 2020). "In addition, we found that dual inhibitors treatment activated Src kinase in our xenograft melanoma model, which accompanied with the upregulation of YAP1 protein level." (PMID 35006410, 2020). "Therefore, we further investigated the role of YAP1 in the development of melanoma." (PMID 38515849, 2024). "Similarly, the number of cyclin D1+ cells was also increased in YAP1 melanomas." (PMID 38308096, 2024). "In addition, the correlation of YAP1/TAZ with the MITFlow/AXLhigh phenotype was significant across the TCGA melanoma tumors and clinically resistant melanoma samples amongst which a subset of resistant tumors acquired YAP1 activity along with clinical resistance toward MAPK inhibitors." (PMID 35798875, 2022). "Significantly more genes were either up-regulated or down-regulated following TAZ knockdown compared to YAP1 knockdown, indicating that TAZ has a major role in regulating gene expression in SOX10 KO melanoma cells." (PMID 41193428, 2025). "Next, we compared our RNA-seq data to four previously established YAP1/TAZ gene signatures (Cordenonsi YAP UP50, White YAP/TAZ51, Harvey Melanoma Up, and Harvey Melanoma Down47)." (PMID 41193428, 2025). "The integrins activate Src-YAP1, thereby conferring dual resistance to MAPK and PI3K/mTOR inhibitors to melanoma cells." (PMID 40243917, 2025). "We observed a greater enrichment in all 4 gene sets following TAZ knockdown compared to YAP1 knockdown, suggesting that TAZ is responsible in melanoma cells depleted of SOX10 for mediating the expression of genes associated with these YAP1/TAZ signatures." (PMID 41193428, 2025). "Thus, suppression of YAP1 might improve the therapeutic effect of trametinib in melanoma patients." (PMID 38169595, 2024). "Previously, we showed that YAP1 is highly expressed in the nuclei of CAFs in human melanoma, and the biological functions of stromal fibroblasts, especially their extracellular matrix (ECM)-remodeling ability, are inhibited when YAP1 expression is silenced." (PMID 38308096, 2024). "Immunofluorescence analysis showed that YAP1 was translocated into the nucleus after trametinib treatment in A375 and SK-MEL-28 melanoma cells." (PMID 38169595, 2024). "Depletion of YAP1 in the A375 and SK-MEL-28 cell lines significantly inhibited the proliferation of melanoma cells." (PMID 38169595, 2024). "The results demonstrated that the overexpression of YAP1 in A375 and SK-MEL-28 significantly enhanced the proliferation of melanoma cells." (PMID 38169595, 2024). "The data demonstrated that the N-cadherin-N-cadherin tumor-stroma interaction is indeed modulated by YAP1 signaling in CAFs, and the AKT signaling pathway is an N-cadherin downstream pathway in melanoma cells." (PMID 38308096, 2024). "These include some canonical melanoma tumor-suppressive genes such as BRD9 and CDKN2A/CDKN2B, and several critical melanoma oncogenes like BIRC5 and YAP1." (PMID 37904237, 2023). "Amongst YAP1/TAZ target genes overexpressed in both YAP5SA melanoma cell lines, only VGLL3 scored as essential in untreated YAP5SA melanoma cells." (PMID 35798875, 2022). "Single gene knock-outs showed modest re-sensitization to Vemurafenib, whereas simultaneous knockout of both YAP1 and TAZ revealed pronounced re-sensitization in MITFlow/AXLhigh melanoma cells." (PMID 35798875, 2022). "We transduced the BRAFV600E mutant melanoma cell lines A375 and SKMEL28 with a lentiviral vector expressing a constitutively active mutant of YAP1 (YAP5SA) to induce YAP1 activity, which was confirmed using a luciferase reporter." (PMID 35798875, 2022). "As YAP1 stimulated the expression of RTKs and their ligands, we first assessed RTK activity in YAP5SA melanoma cells compared to controls using phospho-RTK arrays." (PMID 35798875, 2022).
melanoma (continued). "Co-treatment of inhibition of YAP1 activity and PLX 4032 has been confirmed as a feasible treatment for BRAF-resistant melanoma derived from cancer stem cells." (PMID 33996543, 2021). "Hippo effectors YAP1 and TAZ contribute to multiple cancers’ metastatic behavior, including melanoma." (PMID 33803640, 2021). "Significantly, enrichment of the YAP1 and ECM gene signature is also found in clinical melanoma specimens, suggesting the possible application of YAP1 or ROCK inhibition together with MAPK inhibitors in preventing the onset of resistance." (PMID 32466585, 2020). "Together with YAP1/TAZ, MRTFA is another central mediator of mechanical stimuli also involved in the acquisition of MAPKi resistance in melanoma cells." (PMID 32466585, 2020). "In conclusion, our data not only illuminated an integrin-Src-YAP1 pathway mediated MAPKi and PI3K/mTORi dual-drug resistant mechanism but also provided a potential combinatorial regimen for the drug-relapsed melanoma patients." (PMID 35006410, 2020). "In support of this, c-Fos has recently been described to regulate YAP1 transcriptional activity in the context of KRAS-driven cancers and AP-1/TEAD were found to act as regulators of the invasive gene network in melanoma." (PMID 26295846, 2015). "For example, YAP1 was described to be important for negative durotaxis in melanoma cells and to be less present in the nuclei of well-polarized epithelia." (PMID 39157442, 2024). "We generated a triple transgenic mouse strain, α-SMA-CreERT2; Rosa-rtTA; tetO-Yap1, that inducibly overexpresses YAP1 protein in α-SMA+ fibroblasts and determined whether YAP1-overexpressing α-SMA+ fibroblasts could accelerate melanoma progression." (PMID 38308096, 2024). "In an effort to find YAP1 inhibitors, we screened 102 small molecules that were FDA-approved, in clinical trials, or druglike, and found that the BET inhibitor NHWD-870 strongly suppressed YAP1 expression and melanoma proliferation." (PMID 38169595, 2024). "The number of α-SMA-positive (α-SMA+) CAFs and the surface areas occupied by α-SMA+ cells were reduced in melanomas upon YAP1 ablation albeit CAFs appeared not to be a dominant component of the tumor mass." (PMID 38308096, 2024). "Although there is no inhibitor that acts directly on YAP1 in use in the clinic because of the unstructured nature of YAP1 21, the combinatorial use of indirect inhibitors of YAP1 and MEK inhibitor may serve as an alternative avenue for melanoma treatment." (PMID 38169595, 2024). "Furthermore, tumors formed by YAP5SA-activated melanoma cells in immunodeficient NSG mice grew despite Vemurafenib treatment, confirming YAP1-induced resistance to Vemurafenib in vivo." (PMID 35798875, 2022). "To corroborate the role of YAP1/TAZ as an upstream regulator of the MITFlow/AXLhigh melanoma subclass, and as a driver of resistance to MAPKis across melanoma cell lines and patient tumors, we scored for YAP1/TAZ activity using an established pancancer YAP1/TAZ target gene signature." (PMID 35798875, 2022). "Moreover, melanoma cell lines switch between an MITF-driven proliferative and a YAP1-driven invasive state which both have been demonstrated experimentally to be associated with respective gene signatures." (PMID 35798875, 2022). "Mitf expression is regulated by multiple signaling pathways outside of the canonical Wnt/β-catenin pathway, such as the cAMP/CREB, YAP1/PAX3, TGFβ/GLI2, and TNF/NFκB pathways, and by transcription factors, such as SOX10 and BRN2, themselves regulated by multiple pathways in melanoma." (PMID 35158973, 2022). "Mechanically, YAP1 overexpression in cancer cells could upregulate PD-L1 expression and impede the activities of CD8+ T cells in melanoma." (PMID 36479120, 2022). "Altogether, our data indicate that YAP1/TAZ induce the MAPKi-resistant MITFlow/AXLhigh phenotype in melanoma cells and likely contribute as upstream regulators to MAPKi resistance of BRAFV600E melanoma tumors in the clinic." (PMID 35798875, 2022).
melanoma (continued). "Notably, pharmacological BRAF inhibition further stimulated ERBB3 signaling in YAP1-activated melanoma cells in line with a previous report, highlighting ERBB3 as a particularly relevant target in MAPKi-resistant melanoma cells with high YAP1 activity." (PMID 35798875, 2022). "YAP1 has been shown to contribute to melanoma progression, therefore, we wondered whether LTBP4 affected YAP1 activity." (PMID 35252214, 2021). "That leads us to conclude, that unlike in other models, LATS1 is not a primary kinase for YAP1 inactivating phosphorylation in melanocytes and melanoma." (PMID 33803640, 2021). "Analyzing specific genes involved in phenotypic plasticity, the TCGA dataset confirmed the direct and significant correlation between expression levels of molecules connected to EMT (ZEB1) and stemness (YAP1, ABCC4) molecules, as well as NAMPT in melanoma patients." (PMID 33419372, 2020). "Interestingly, Nallet-Staubet al. have demonstrated that YAP1 and TAZ contribute to the invasive and metastatic capacity of melanoma cells." (PMID 24621512, 2014). "To uncover genetic dependencies of melanoma cells with high YAP1/TAZ activity, we used a genome-wide CRISPR/Cas9 functional screen and identified SLC35B2, the 3′-phosphoadenosine-5′-phosphosulfate transporter of the Golgi apparatus, as an essential gene for YAP1/TAZ-driven drug resistance." (PMID 35798875, 2022). "Interestingly, the MITFlow/AXLintermediate/high melanoma cell lines showed higher YAP1/TAZ activity compared to the engineered YAP5SA cell lines, indicating that the latter reflect a physiological level of high YAP1 activity." (PMID 35798875, 2022). "In addition, expression of EXT1, but not SLC35B2, was positively correlated with the YAP1/TAZ score in the TCGA cohort of BRAF mutant melanoma, suggesting that EXT1 is a YAP1/TAZ target." (PMID 35798875, 2022). "Taken together, these results indicated that integrin/Src/YAP1 axis mediated resistance to MAPK and PI3K/mTOR dual inhibitors, which made it a promising target for the development of combinatorial regimens overcoming MAPK and PI3K/mTOR dual inhibitors–refractory melanoma patients." (PMID 35006410, 2020). "It increases melanoma tumorigenesis and stemness via interaction with MST2 and the inhibition of MST2 homodimer formation and kinase activity, thus reducing LATS activity and enhancing TAZ (but not YAP1) stability." (PMID 38920690, 2024). "While SLC35B2 knockout sensitized YAP1-activated melanoma cells toward Vemurafenib treatment, it did not completely stop melanoma cell proliferation, comparable to the strong, but limited effect of Vemurafenib single treatment on BRAFV600 mutant melanoma cells without YAP1 activation." (PMID 35798875, 2022). "Consistent with the RPPA data, the combination induced strong downregulation of p-AKT, YAP1, p-YAP1 and p-PRAS40 protein expression in Me1007 and Patient-3-post cells and other melanoma cell lines, whereas no change in protein expression could be observed in melanocytes." (PMID 26087189, 2015).
esophageal cancer (50 papers, 2014 to 2026). A primary or metastatic malignant neoplasm involving the esophagus. "Bioinformatics analysis revealed OTUB2 was highly expressed in esophageal cancer and was associated with YAP1/TAZ." (PMID 35850645, 2022). "Increased YAP1 expression in esophageal cancer cells was associated with the acquisition of cancer stem cell (CSC)-like properties." (PMID 36045416, 2022). "High expression of YAP1 was associated with a better OS in esophageal cancer (OS, HR = 0.56, p = 0.012)." (PMID 34150844, 2021). "It has been found that increased expression of Yap1 is associated with the development, progression, and drug resistance of esophageal cancer." (PMID 34712552, 2021). "For example, overexpression of YAP1 was positively associated with CDK6expression in radiation-resistant esophageal cancer tissues (both in OAC and OSCC)." (PMID 33665161, 2020). "In esophageal cancer, the Hippo coactivator Yes-associated protein 1 (YAP1) upregulates SOX9 transcription by binding to the SOX9 promoter, upregulating SOX9 expression, followed by the acquisition of cancer stem cell properties." (PMID 26384302, 2015). "Consistently, we have found a significant association between YAP1 upregulation and cigarette smoking in the clinical esophageal cancer samples." (PMID 24621512, 2014). "Collectively, these observations suggest nAChRs physically associate with YAP1 in esophageal cancer cells." (PMID 24621512, 2014). "Similarly, knockdown of YAP1 increased susceptibility of esophageal cancer cells to 5-fluorouracil and docetaxel." (PMID 41009501, 2025). "Moreover, there was a significant correlation between Ezrin and yes-associated protein/connective tissue growth factor (YAP1/CTGF) levels in esophageal cancer." (PMID 37791063, 2023). "Furthermore, we observed altered physical associations between YAP1 and α-catenin/β-catenin/14-3-3 upon the activation of YAP1 by nicotine administration in esophageal cancer cell." (PMID 24621512, 2014). "For example, YAP1 (yes-associated protein 1; ProGENI rank 2) regulates genes involved in cell proliferation and apoptosis; induction of this gene has been shown to induce resistance to docetaxel, and its knockdown has been shown to sensitize esophageal cancer cells to this drug." (PMID 28800781, 2017). "Further research discovered that Hippo coactivator YAP1 stimulates SOX9 expression in esophageal cancer cells, resulting in these cancer cells exhibiting stem cell-like characteristics." (PMID 37183261, 2023). "Ezrin and YAP1/CTGF expression levels in esophageal cancer tissue were analyzed by immunohistochemistry." (PMID 37791063, 2023). "The overall survival time of patients with overexpression of YAP1 in esophageal cancer is longer than those with low expression, which is contrary to our results of meta-analysis (MST: 1361 vs. 763 days, P < 0.0001)." (PMID 35911146, 2022). "Although earlier studies imply activation of APE1 and YAP1 in esophageal cancer; the mechanistic relationship between these two proteins and their regulation in response to reflux conditions in EAC remains undetermined." (PMID 36045416, 2022). "It was shown that the YAP1/TEAD complex transcriptionally regulates the SOX9 gene in esophageal cancer." (PMID 36180487, 2022). "Together, both the knockdown and overexpression data support a suppressive function of YAP1 in regulating esophageal cancer cell proliferation, migration and invasion." (PMID 35930163, 2022). "In support of our in vitro studies and experimental tumorigenesis, we found that an increase in YAP1 expression predicts a better overall survival among esophageal cancer patients in the TCGA cohort." (PMID 35930163, 2022). "We detected a persistent increase in TAZ protein expression without a corresponding increase of its mRNA expression level in most YAP1-depleted esophageal cancer cells, except those depleted by shYAP1#2." (PMID 35930163, 2022).